SOCS5 (suppressor of cytokine signaling 5)
Diseases named in the same sentence as SOCS5 in open-access papers (continued):
Sharing a sentence is not in itself a finding about the gene and the disease.
influenza infection (5 papers, 2014 to 2025). "SOCS5-deficient mice were more likely to become infected with influenza and respond with an increased presence of pro-inflammatory cytokines in pulmonary epithelium." (PMID 40725399, 2025). "Secondly, despite the validity of PI3K as a potential SOCS5 target, the increased susceptibility of Socs5−/− mice to influenza is due to altered EGFR signaling." (PMID 28195529, 2017). "Collectively, these data suggest that the heightened susceptibility to influenza observed in Socs5−/− mice results from a defect in the lung epithelium, with the increased viral titre in the Socs5−/− lungs initiating an inflammatory cascade that is driven primarily by neutrophil infiltration." (PMID 28195529, 2017). "This suggests that SOCS5 might be an important factor in the susceptibility of these patients to influenza." (PMID 28195529, 2017). "A study further reported that SOCS5 improved control of influenza infection by inhibiting EGFR signaling." (PMID 33758600, 2021). "SOCS5 levels are reduced in hAECs from COPD patients and a highly pathogenic avian virus (H5N1) actively reduced SOCS5 expression, thus linking SOCS5 to influenza pathogenesis." (PMID 28195529, 2017). "The Socs5−/− mice present a novel model of exacerbated human influenza, displaying increased viral load, exaggerated cytokine production in the early phase of the infection and increased neutrophil trafficking into the airways." (PMID 28195529, 2017). "SOCS1 and SOCS3 expression has been associated with symptomatic influenza infection, whereas SOCS2 and SOCS5 have been linked to asymptomatic disease." (PMID 24809749, 2014). "In addition, inhibition of EGFR/PI3K signaling by SOCS5 conferred protection against influenza infection." (PMID 32038638, 2019). "Our data position SOCS5 as a pivotal regulator of influenza, a major global disease." (PMID 28195529, 2017). "Socs5 levels were differentially regulated in response to distinct influenza viruses (H1N1, H3N2, H5N1 and H11N9) and were reduced in primary epithelial cells from COPD patients, again correlating with increased susceptibility to influenza." (PMID 28195529, 2017). "We suggest that SOCS5 acts as a central switch point, with changes in SOCS5 levels and/or activity impacting disease outcome in individuals such as those with COPD, who exhibit increased susceptibility to influenza." (PMID 28195529, 2017). "The next is step is to understand exactly how SOCS5 works, which may make it possible to develop new treatments that boost SOCS5 activity in influenza patients." (PMID 28195529, 2017). "Importantly, restoration of SOCS5 levels restricted influenza virus infection, suggesting that manipulating SOCS5 expression and/or SOCS5 targets might be a novel therapeutic approach to influenza." (PMID 28195529, 2017). "Further experiments in lung cells collected from human volunteers show that SOCS5 levels increased in both healthy smokers and non-smokers in response to influenza infection." (PMID 28195529, 2017).
chronic obstructive pulmonary disease (4 papers, 2021 to 2025). A chronic and progressive lung disorder characterized by the loss of elasticity of the bronchial tree and the air sacs, destruction of the air sacs wall, thickening of the bronchial wall, and mucous accumulation in the bronchial tree. "Reduced expression of SOCS5 is found in chronic obstructive pulmonary disease, while in pulmonary hypertension, the downregulation of SOCS5 has led to abnormal proliferation and contraction of pulmonary muscle cells." (PMID 40725399, 2025). "During chronic obstructive pulmonary disease progression, miR-132 overexpression targeted and inhibited SOCS5, thereby promoting EGFR protein expression and inflammatory cytokine production in human mononuclear cells." (PMID 38267898, 2024). "Moreover, targeted inhibition of SOCS5 by upregulated miR-132 promoted the progression of chronic obstructive pulmonary disease." (PMID 38267898, 2024). "Interestingly, epithelial cells from chronic obstructive pulmonary disease (COPD) patients displaying increased susceptibility to IAV infections have reduced SOCS5 levels, suggesting SOCS5 substrates may represent new anti-viral drug targets." (PMID 35083168, 2021). "Patients with chronic obstructive pulmonary disease (COPD) have been found to have decreased SOCS5 levels, which underpins heightened levels of IL-1β and TNFα." (PMID 39676878, 2024).
leukemia (4 papers, 2021 to 2024). A malignant (clonal) hematologic disorder, involving hematopoietic stem cells and characterized by the presence of primitive or atypical myeloid or lymphoid cells in the bone marrow and the blood. "The authors postulated that SOCS5 inactivation accelerate leukaemia burden and progression of the disease." (PMID 39676878, 2024). "sought to elucidate the regulatory roles of SOCS5 in leukaemia and cellular signalling and found that genetic silencing of SOCS5 induces JAK-STAT signalling activation, and negatively regulates some interleukins." (PMID 39676878, 2024). "Taken together, leonurine exerts significant anti-leukemia efficacy in CML by regulating miR-18a-5p/SOCS5/JAK2/STAT3 axis." (PMID 33935775, 2021). "Silencing of SOCS5 by its siRNA abrogated the effect of leonurine on CML cells, demonstrating that SOCS5 mediates the anti-leukemia effect of leonurine." (PMID 33935775, 2021). "The anti-leukemia activity of leonurine was illustrated by regulating miR-18a-5p/SOCS5/JAK2/STAT3 axis." (PMID 33935775, 2021). "A previous study showed that Leonurine plays an anti-leukemia role by inhibiting the proliferation, migration and colony formation of chronic myeloid leukemia cells and promoting their apoptosis through the miR-18a-5p/SOCS5/JAK2/STAT3 axis." (PMID 38267898, 2024). "Our results indicated that SOCS5/JAK2/STAT3 was involved in anti-leukemia process of leonurine and that SOCS5 may be a potential diagnostic marker and therapeutic target for CML." (PMID 33935775, 2021). "Leonurine down-regulates miR-18a-5p and enhances SOCS5 expression to curb JAK2/STAT3 signaling pathway activation, impeding CML cells’ proliferation, migration, and colony formation, boosting their apoptosis, and thus exerting a prominent anti-leukemia function in chronic myeloid leukemia." (PMID 36333771, 2022).
lung cancer (4 papers, 2020 to 2024). A malignant neoplasm involving the lung. "Upregulation of SOCS5 was associated with inhibition of cell viability, migration and invasion in non‐small cell lung cancer." (PMID 38267898, 2024). "miR-522–3p was found to directly target SOCS5 to promote lung cancer cell viability, migration and invasion." (PMID 33935775, 2021).
colon carcinoma (3 papers, 2021 to 2024). "The current study aimed to investigate the effect of valproic acid (VPA) on SOCS-1, SOCS-2, SOCS-3, SOCS-5, SOCS6, and SOCS-7 gene expression and cell growth inhibition in colon carcinoma IS1, IS2, and IS3 cell lines." (PMID 35611249, 2022). "The results of the current study demonstrate that VPA plays its role through the upregulation of SOCS-1, SOCS-2, SOCS-3, SOCS-5, SOCS6, and SOCS-7 genes, resulting in cell growth inhibition and apoptosis induction in colon carcinoma IS1, IS2, and IS3 cell lines." (PMID 35611249, 2022).
inflammatory bowel disease (3 papers, 2022 to 2024). A spectrum of small and large bowel inflammatory diseases of unknown etiology. "Remarkably, miR-802 increases Th17 immune response by targeting the suppressor of cytokine signaling (SOCS5) in inflammatory bowel disease." (PMID 35370692, 2022).
prostate carcinoma (3 papers, 2016 to 2023). A carcinoma that arises from epithelial cells of the prostate gland. "Luciferase constructs of the e-cadherin and SOCS5 3’-UTRs showed that miR-9 suppression is effective in this prostate cancer model and is due to direct binding of miR-9 to mRNA target sequences." (PMID 27447934, 2016).
acute pancreatitis (2 papers, 2022 to 2024). An acute inflammatory process that leads to necrosis of the pancreatic parenchyma. "In severe acute pancreatitis induced acute lung injury, stellate ganglion block promoted the expression of SOCS5, inhibited the expression of miR-155-5p, and inhibited the activation of JAK2/STAT3 pathway." (PMID 38267898, 2024). "Consistent with our results, SOCS5 was significantly reduced in the lung tissues of severe acute pancreatitis-induced acute lung injury rats." (PMID 38267898, 2024).
allergic asthma (2 papers, 2023 to 2024). A asthma with a basis in a pathological type I hypersensitivity reaction. "In an allergic asthma model, high levels of SOCS5 in transgenic mice resulted in increased Th2 responses and eosinophilic inflammation, suggesting that SOCS5 overexpression in Th2-dominated diseases is not a useful therapeutic target." (PMID 38534350, 2024). "CISH knockout mice showed increased susceptibility to experimental allergic asthma and EAE, while SOCS5 was preferentially expressed in the retina and significantly upregulated during the development and resolution EAU." (PMID 36969252, 2023).
allergic disease (2 papers, 2023 to 2025). An immune response that occurs following re-exposure to an innocuous antigen, and that requires the presence of existing antibodies against that antigen. "Such reciprocal inhibition between SOCS3 (Th2-associated) and SOCS5 (Th1-associated) underpins the Th1/Th2 imbalance observed in allergic diseases." (PMID 40568590, 2025).
cholangiocarcinoma (2 papers, 2021 to 2024). A carcinoma that arises from the intrahepatic biliary tree (intrahepatic cholangiocarcinoma) or from the junction, or adjacent to the junction, of the right and left hepatic ducts (hilar cholangiocarcinoma). "However, the integration of our data with existing literature on the CASC2/miR-18a/SOCS5 axis provides a deeper understanding of the molecular mechanisms underpinning cholangiocarcinoma and highlights potential avenues for therapeutic intervention." (PMID 39458127, 2024). "Notably, a previous study showed that miR-18a-5p could target SOCS5 and regulate its expression in cholangiocarcinoma." (PMID 33935775, 2021).
chronic lymphocytic leukemia (2 papers, 2016 to 2021). "Although SOCS5 dysregulation has been recently associated with acute and chronic lymphocytic leukemia, its role in CML has not been characterized to date." (PMID 33935775, 2021).
osteosarcoma (2 papers, 2022 to 2024). A usually aggressive malignant bone-forming mesenchymal neoplasm, predominantly affecting adolescents and young adults. "Fer-1-like protein 4 (FER1L4) prevented EMT initiation, controlling osteosarcoma cell proliferation via miR-18a-5p/SOCS5/PI3K/AKT signaling pathway." (PMID 38948025, 2024).
pulmonary hypertension (2 papers, 2024 to 2025). Increased pressure within the pulmonary circulation due to lung or heart disorder. "In this study, we investigated the potential role of SOCS5 in experimental pulmonary hypertension and underlying mechanisms." (PMID 38267898, 2024).
anxiety disorder (1 paper, 2024). A category of psychiatric disorders which are characterized by anxious feelings or fear often accompanied by physical symptoms associated with anxiety. "For anxiety disorders, 18 SNPs are linked to genes including CAMKMT, ARPP19, SOCS5, TNS3, VWDE, TSHZ2, and others." (PMID 39165506, 2024).
autoimmune disease (1 paper, 2025). A disorder resulting from loss of function or tissue destruction of an organ or multiple organs, arising from humoral or cellular immune responses of the individual to their own tissue constituents. "The pathogenic mechanisms of autoimmune diseases are complex, and SOCS proteins, particularly SOCS1, SOCS2, SOCS3, and SOCS5, regulate cytokine receptor signaling through distinct mechanisms, thereby participating in the development and progression of autoimmune diseases." (PMID 40755762, 2025).
Cirrhosis (1 paper, 2024). A chronic disorder of the liver in which liver tissue becomes scarred and is partially replaced by regenerative nodules and fibrotic tissue resulting in loss of liver function. "According to the IHC score, 216 HCC with HBV-related cirrhosis patients from 2013 to 2016 were divided into a SOCS5 high expression group (n = 113) and a SOCS5 low expression group (n = 103)." (PMID 38429411, 2024). "In our patient cohort, when compared to the SOCS5 low-expression group (n = 120), high expression of SOCS5 (n = 125) was positively correlated with steatosis, cirrhosis, and longer tumor diameters of HCC, and serum total bile acid levels were higher." (PMID 38429411, 2024). "Similarly, 216 HCC with HBV-related cirrhosis patients from 2013 to 2016 were divided into an SOCS5 high expression group (n = 113) and an SOCS5 low expression group (n = 103)." (PMID 38429411, 2024). "In the Gao’s HBV-related cirrhosis HCC cohort and GSE121248’s HBV-related HCC cohort, we found that high expression of SOCS5 predicts increased FA synthesis, and SOCS5, as one of the driver genes for SBC-HCC, is upregulated in SBC-HCC." (PMID 38429411, 2024). "In Gao’s HBV-related cirrhosis HCC cohort, the High SOCS5 group had a higher score of FA Biosynthesis than the Low SOCS5 group (p < 0.05), and the expression of SOCS5 in the High-lipid group was upregulated compared to the Low-lipid group (p < 0.05)." (PMID 38429411, 2024). "Screening for driver genes promoting fatty acid (FA) biosynthesis in the Gao’s HBV-related cirrhosis HCC cases and GSE121248’ HBV-related HCC cases revealed that high expression of SOCS5 predicts increased FA synthesis and that SOCS5 is upregulated in SBC-HCC." (PMID 38429411, 2024).
diabetic nephropathy (1 paper, 2021). "Studies on diabetic nephropathy indicated that Angpt2 promotes autophagy in MCs through miR‐33‐5p/SOCS5 loop." (PMID 33987885, 2021).
diabetic retinopathy (1 paper, 2026). "This study elucidated the mechanistic role of the Suppressor of Cytokine Signaling 5 (SOCS5) in diabetic retinopathy (DR), focusing on DNA damage and cellular senescence pathways." (PMID 41922309, 2026).
esophageal cancer (1 paper, 2021). A primary or metastatic malignant neoplasm involving the esophagus. "Because SOCS5 seems to be correlated with distant metastasis of esophageal cancer, we finally investigated the effects of SOCS5 on cell migration by wound-healing assay." (PMID 33758600, 2021).
esophageal tumor (1 paper, 2021). "Our results reveal a difference in the clinical impact of SOCS5 expression in adjacent normal tissue compared to esophageal tumor tissue." (PMID 33758600, 2021).
hypothyroidism (1 paper, 2014). Abnormally low levels of thyroid hormone. "The level of SOCS3 mRNA was induced by hypothyroidism itself, whereas neither hypothyroidism nor hormonal replacement altered SOCS5." (PMID 24816529, 2014).
metastatic disease (1 paper, 2013). "In conclusion, this study identifies two distinct mechanisms by which SOCS5 can regulate cytokine and growth factor signaling, and positions SOCS5 as a potential regulator of multiple growth and chemotactic stimuli, many of which are pivotal to cellular transformation and metastatic disease." (PMID 23990909, 2013).
non-alcoholic steatohepatitis (1 paper, 2023). "Specifically, TNFSF14 and GAD1 are highly expressed in HCC; STARD1 promotes the progression of non-alcoholic steatohepatitis to HCC via bile acids; DHRS4-AS1 ameliorates HCC by suppressing proliferation and promoting apoptosis via the miR-522-3p/SOCS5 axis." (PMID 36899918, 2023).
oral squamous cell carcinoma (1 paper, 2022). "In oral squamous cell carcinoma (OSCC) and CML, MEG3 promoted apoptosis by sponging miR-548d-3p and miR-147, thereby promoting suppressor of cytokine signaling 5 (SOCS5) and suppressor of cytokine signaling 6 (SOCS6) expression while inhibiting the JAK-STAT signaling pathway." (PMID 36551518, 2022).
pancreatitis (1 paper, 2022). Inflammation of the pancreas. "Notwithstanding, we are still in the dark about the mechanism of the SOCS5/JAK2/STAT3 pathway in lung damage elicited by pancreatitis." (PMID 36333771, 2022). "Therefore, a probe into the JAK2/STAT3 pathway mediated by SOCS5 helps us better understand the exact mechanism of lung damage elicited by pancreatitis." (PMID 36333771, 2022).
periodontitis (1 paper, 2022). An acute or chronic inflammatory process that affects the tissues that surround and support the teeth. "Thus, we measured expression levels of SOCS1-3 and SOCS5 transcripts in the circulation and gingiva of patients with periodontitis in comparison with control samples obtained during dental crown lengthening." (PMID 36456933, 2022). "Thus, we measured expression levels of SOCS1-3 and SOCS5 transcripts in the blood and gingival samples of patients with periodontitis in comparison with control samples obtained during dental crown lengthening." (PMID 36456933, 2022).
T-cell acute lymphoblastic leukemia (1 paper, 2020). Acute lymphoblastic leukemia of T-cell origin. "A recent report suggests that epigenetic silencing of Socs5 potentiates JAK-STAT signaling and progression of T-cell acute lymphoblastic leukemia." (PMID 33378745, 2020).
thyroid cancer (1 paper, 2021). "Finally, SOCS5 contribute in the pathogenesis of uveitis and thyroid cancer." (PMID 34349769, 2021).
urticaria (1 paper, 2025). A vascular reaction of the skin characterized by erythema and wheal formation due to localized increase of vascular permeability. "Variations in several other genes, such as SOCS5, FLG and angiotensin‐converting enzyme, are known to increase the susceptibility of other multisystem immune‐related disorders, but their role in urticaria remains to be identified." (PMID 40635160, 2025).